TBX5 (T-box transcription factor 5)
Diseases named in the same sentence as TBX5 in open-access papers (continued):
Sharing a sentence is not in itself a finding about the gene and the disease.
colon cancer (22 papers, 2011 to 2024). "Rosenbluh reported that in the development of colon cancer, the compounds formed by β-catenin, yes-associated protein 1 (YAP1) and TBX5 were essential for survival of colon cancer, similar phenomena were observed in other tumors." (PMID 38413457, 2024). "TBX5 is a transcription factor that has been implicated as a tumor suppressor in colon cancer and has been found silenced by DNA methylation." (PMID 25146004, 2014). "Furthermore, loss of TBX5 expression in colon cancer is epigenetically controlled by promoter methylation and associated with poor prognosis." (PMID 21954337, 2011). "However, in colon cancer, hypermethylation of the CpG island of the TBX5 promoter results in the inability of the promoter region to bind transcription-associated proteins, inhibiting TBX5 transcriptional activity leads to the development of malignant tumors." (PMID 38965548, 2024). "Although a similar phenomenon was described during apoptosis induced by anticancer drugs in colon cancer cells and apoptosis in mitochondrial myopathy, mitochondrial proliferation accompanied by mitochondrial swelling was first reported in apoptosis of zebrafish embryos with tbx5 deficiency." (PMID 21982178, 2011). "Studies have shown that TBX5 dysregulation plays an important role in breast cancer, gastric cancer, oesophageal carcinoma, and colon cancer." (PMID 34238250, 2021). "Another study has been demonstrated that this agent restores the expression of TBX5 in colon cancer cell lines SW620, HT-29, SW620 and CaCO2." (PMID 34466608, 2020). "Recently, TBX5 was illustrated as a novel tumour suppressor and assessed for its potential use as a biomarker for colon cancer." (PMID 28782180, 2018). "Ectopic over-expression of TBX5 protein was demonstrated to inhibit colon cancer cell proliferation and induce apoptosis thus functioning as a putative tumor suppressor." (PMID 28978111, 2017). "However, TBX5 functions as a tumor suppressor in colon cancer cells by inhibiting cell proliferation and inducing apoptosis." (PMID 38965548, 2024). "For instance, in colon cancer, TBX5 has a high degree of methylation and a low expression level." (PMID 35003317, 2021). "Further, TBX5 may act as a novel tumor suppressor gene, which is inactivated by promoter methylation in colon cancer cells." (PMID 33447348, 2020). "TBX5 was also shown to be epigenetically inactivated by promoter methylation in colon cancer." (PMID 30866410, 2019). "Interestingly, TBX5 was reported as a tumor suppressor and recognized as a biomarker for colon cancer." (PMID 29545315, 2018). "TBX5 is a member of a phylogenetically conserved family of genes involved in the regulation of development,it is a novel functional tumor suppressor gene inactivated by promoter methylation in colon cancer." (PMID 29169318, 2017). "Consequently, ChIP analysis was performed to test the association of the β-catenin and YAP protein to the predicted TBX5 sites in colon cancer SW480 cells in which Wnt signaling was activated." (PMID 26415221, 2015). "Second, YAP collaborates with other transcription regulators to alter gene expression, for example, in colon cancer cell lines YAP1, β-catenin, and TBX5 transcriptional complex regulate (TCF- or TEAD-independent) target genes." (PMID 38730720, 2024). "In the GCSC database, the methylation levels of FGF8, NOG, TCF15, TWIST1, TBX5, SIX2, and TIAM1 are higher in colon cancer." (PMID 34526059, 2021). "Additionally, different from TBX5 expression in colon cancer, the expression of TBX4 in PDAC seems not to be DNA methylation-regulated." (PMID 21954337, 2011).
septal defects (19 papers, 2010 to 2025). "Mutations in key transcription factors such as GATA4, NKX2-5, and TBX5, which regulate cardiac development, have been linked to defects such as atrial and ventricular septal defects and TOF." (PMID 40564627, 2025). "Nevertheless, the epigenetic mechanisms of the TBX5 gene associated with congenital septal defects have been scarcely studied." (PMID 35053095, 2022). "TBX5 variants in the region encoding the T-box domain have been shown to cause cardiac defects, such as atrial septal defect or ventricular septal defect, while TBX5 variants have also been identified in a few cardiomyopathy patients and considered causative." (PMID 32236096, 2020). "One notable study demonstrated that GATA4 mutations associated with atrial septal defects (ASDs) disrupt transcriptional networks responsible for atrial specification, impairing key signaling pathways such as Sonic Hedgehog and altering TBX5 recruitment at cardiac enhancers." (PMID 40564627, 2025). "Our results showed significant differences in methylation levels when comparing patients with congenital septal defects to the controls, which suggests that the TBX5 gene could be a marker for risk association with septal defects." (PMID 35053095, 2022). "In conclusion, our data suggest that a high DNA methylation of the TBX5 gene could be associated with congenital septal defects; additionally, environmental factors during pregnancy also confer a risk of developing congenital septal defects." (PMID 35053095, 2022). "Additionally, the mothers of individuals with septal defects were analysed with regard to their exposure to environmental risk factors during pregnancy; likewise, we made a bioinformatics analysis in the promoter region of the TBX5 gene." (PMID 35053095, 2022). "Genetic mutations in cardiac transcription factor genes such as NKX2-5, GATA4, TBX5 and MYH6, located in chromosome 14q12, have been associated with atrial septal defects." (PMID 40843896, 2025). "The genes in this cluster included Nkx2-5, Myh6, Tbx5, and ten others, which were preferentially related to the CHDs like atrial septal defect (ASD) and ventricular septal defect (VSD)." (PMID 36575170, 2022). "Deleterious TBX5, NKX2-5, and GATA4 mutations are found in individuals with congenital heart disease, including atrial septal defects." (PMID 36362216, 2022). "The mutations in various genes have been associated with atrial septal defects, for instance, mutations in NKX2–5, GATA4, TBX5, and MYH6." (PMID 29969989, 2018). "The majority of cases are sporadic, but some are inherited and associated with mutations in specific genes such as NKX2-5 (also associated with atrioventricular conduction defects), GATA4, TBX5 (associated with Holt–Oram syndrome) and MYH6 (implied in septal defects)." (PMID 40843896, 2025). "Therefore, we performed a case-control study, that involved the DNA methylation assessment of the TBX5 gene promoter region in patients that were non-syndromic with congenital septal defects, to identify an epigenetic marker." (PMID 35053095, 2022). "For example, in the case of atrial septal defect (ASD) and ventricular septal defect (VSD), candidate genes can be counted: NKX2-5, GATA4, TBX20, MYH6, and TBX5, while the pathogenesis of atrioventricular septal defect (AVSD) involves genes, such as PTPN11, KRAS, SOS1, RAF1, and CRELD1." (PMID 34946970, 2021).
atrial fibrillation (18 papers, 2013 to 2024). A disorder characterized by an electrocardiographic finding of a supraventricular arrhythmia characterized by the replacement of consistent P waves by rapid oscillations or fibrillatory waves that vary in size, shape and timing and are accompanied by an irregular ventricular response. "Reduced Tbx5 expression in adult mice disrupts the expression of calcium handling and AF-susceptibility genes, reducing myocardial automaticity and elevating atrial fibrillation susceptibility, these phenotypes can be rescued by Pitx2 haploinsufficiency." (PMID 38643172, 2024). "Tbx5G125R/+ mice were morphologically unaffected and displayed variable RR intervals, atrial extra systoles, and susceptibility to atrial fibrillation, reminiscent of TBX5-p.G125R patients." (PMID 35113653, 2022). "Tbx5 deletion in the adult mouse induced spontaneous and sustained atrial fibrillation with disruption of AF-susceptibility genes." (PMID 32193645, 2020). "TBX5 haploinsufficiency causes congenital conduction disorders, whereas increased expression levels of TBX5 in human heart samples has been associated with atrial fibrillation (AF)." (PMID 36715501, 2023). "A gain-of-function TBX5 gene mutation is associated with atypical HOS and paroxysmal atrial fibrillation." (PMID 31775637, 2019). "Intron variants of TBX5 gene is associated with PR interval, QRS duration and QT interval, as well as atrial fibrillation." (PMID 31775637, 2019). "Individuals with mutations in a gene called Tbx5 are more likely to develop atrial fibrillation than other people, but it was not clear how such gene mutations contribute to the disease." (PMID 30896405, 2019). "This extended gene network contained a number of transcription factors (Tbx5, Hand2, Fhl2, and Gata4) and ion/calcium handling genes (Ank2, Cacna2d2, Scn5a, Kcnd2, Kcnj5, Myoz2, Casq2, Csrp3, and Gja3) of interest in the context of atrial fibrillation." (PMID 28720711, 2017). "Recent genome-wide association studies found that the single-nucleotide polymorphism (SNP) rs3825214 in T-box 5 (TBX5) was positively associated with PR interval, QRS duration, QT interval, and common arrhythmia disorders such as atrial fibrillation (AF) and advanced atrioventricular block." (PMID 23717681, 2013). "Transcription factors TBX5 and PITX2 involve in the regulation of gene expression of ion channels and are closely associated with atrial fibrillation (AF), the most common cardiac arrhythmia in developed countries." (PMID 30353147, 2018). "Two recent studies have demonstrated that TBX5 regulates a network of cardiac channel genes, including RyR2 and SERCA2, to maintain cardiac rhythm, which is involved in atrial fibrillation." (PMID 35167494, 2022). "Notably, genetic and familial studies indicate cardiac transcription factors including GATA4, TBX5, and NKX2.5 in atrial fibrillation pathogenesis." (PMID 38049901, 2023).
ventricular septal defect (14 papers, 2013 to 2025). The presence of a defect (opening) in the septum that separates the two ventricles of the heart. "NF1 and GLI3 are both linked with multiple forms of CHDs, including atrial and ventricular septal defects, which are common forms of CHDs that are also associated with CHD genes such as NKX2–5 and TBX5." (PMID 40857331, 2025). "Several such mutations have been identified with developmental disorders such as atrial septal defect (ASD) associated with a mutation in GATA4 gene, and genes TBX5, TBX20 have been identified to result in ventricular septal defect (VSD) and left ventricular non-compaction (LVNC)." (PMID 35317745, 2022).
Arrhythmia (13 papers, 2018 to 2025). Any cardiac rhythm other than the normal sinus rhythm. "T-box 5 (TBX5) is a key transcription factor involved in cardiac development, has been shown to play a crucial role—loss of ventricular TBX5 causes cardiac dysfunction and sudden death due to arrhythmias." (PMID 41179895, 2025). "We report the relatively large effect of this modest increase in Tbx5 expression on atrial function including arrhythmia susceptibility, and on the gene regulatory network." (PMID 36715501, 2023). "Together, our data show that a slight increase in Tbx5 disturbs atrial function and can predispose to arrhythmia." (PMID 36715501, 2023). "Our data reveal that a disease-causing missense variant in TBX5 induces profound changes in the atrial transcriptional regulatory network and epigenetic state in vivo, leading to arrhythmia reminiscent of those seen in human TBX5-p.G125R variant carriers." (PMID 35113653, 2022). "Transcriptional profiling of the atria showed that heterozygosity of Tbx5-p.G125R leads to extensive dysregulation of gene expression in the atria, indicating multiple and complex mechanisms underlie the arrhythmia phenotype." (PMID 35113653, 2022). "To illustrate this point, we highlight two genes: TBX5, a gene directly linked to cardiac arrhythmia, and LITAF, a gene that, until recently, had no obvious role in cardiac biology." (PMID 29988018, 2018). "This is consistent with the observed longer atrial APD in Tbx5RE(int)KO mice compared to controls, which may predispose to increased arrhythmia inducibility, as seen in mice harboring the pathogenic TBX5-G125R variant or Prrx1 enhancer deletion." (PMID 36715501, 2023). "Systemic delivery of AAV9-TBX5 in knockout mice normalized TBX5 protein level and re-established TBX5-dependent transcriptome, resulting in reduced arrhythmia and improved cardiac function." (PMID 41179895, 2025). "miR-182-5p exerted an evolutionarily conserved role as a TBX5 effector in the onset of cardiac propensity for arrhythmia in zebrafish, thereby mediating the relationship between TBX5, arrhythmia, and heart development." (PMID 36936432, 2023). "Our study reveals that atrial- and postnatal-specific increase in Tbx5 levels of only 30% affects postnatal atrial gene regulation, function and arrhythmia propensity." (PMID 36715501, 2023). "The knockout of TBX5 from the mature murine ventricular conduction system markedly decreases the density of NaV1.5, increases arrhythmias propensity, and results in sudden cardiac death." (PMID 33391024, 2020). "Several studies have reported that MM patients treated with thalidomide experienced arrhythmias or congenital septal defects (following its administration to pregnant women), which may be related to the interaction of the cardioprotective-related TBX5 transcriptional activator." (PMID 36532784, 2022). "Multiple downstream genes regulated by TBX5, F2R, and SFRP4 were involved in ICM-related diseases such as HF and arrhythmia." (PMID 32423033, 2020). "For example, the terms cardiac muscle contraction or regulation of ventricular cardiac muscle cell depolarization were enriched for Cardiac Arrhythmia, including genes such as Gap Junction Protein Alpha 1 (GJA) and T-Box Transcription Factor 5 (TBX5) with known roles in the disease." (PMID 37491351, 2023). "Integrating the results of the TBX5-targeted genes and the DEGs in toxicity pathways, we found that the dysregulation of TBX5-targeted genes, TNNT2, NPPA, TTN, ATP2A2, DES and SCN5A, contributed to the development of heart failure and arrhythmia." (PMID 32423033, 2020). "TBX5-targeted genes, MYH6, ACTC1 and TPM1, were involved in arrhythmia." (PMID 32423033, 2020).
lung carcinoma (12 papers, 2015 to 2024). "Surprisingly, low expression of TBX5 turned out to be associated with a decrease in OS, which predicted a poor prognosis in lung cancer." (PMID 38413457, 2024). "TBX5 is generally low in nonsmall cell lung cancer, and upregulation of TBX5 markedly represses progression of cancer cells." (PMID 35003317, 2021). "We reviewed the association between the expression of TBX2 subfamily and the prognosis, and explore the research progress of TBX5 in regulating the development and progression of lung cancer." (PMID 32810974, 2020). "In contrast, TBX5 induces apoptosis and inhibits the growth of human osteosarcomas and lung carcinomas." (PMID 33447348, 2020). "Western blots using up to 25 μg of nuclear extracts showed very little or undetected expression of TBX2, TBX3, and TBX5 in all tested lung cancer cell lines while only HBEC2 cells expressed TBX5 which is consistent with qPCR results." (PMID 30425966, 2018). "Moreover, Zhang and colleagues showed that TBX5 mRNA was down-regulated across different subtypes of lung cancer including small-cell lung carcinomas." (PMID 30866410, 2019). "The relationships of two other TFs including MEIS1 and TBX5 with lung cancer are unclear." (PMID 26035298, 2015). "However, our research finding proved that the expression of TBX5 was downregulated in lung cancer." (PMID 38413457, 2024). "We also performed in vitro experiments to explore the functional role of other methylation drivers (IRX1, TBX5 and HSPB6) in lung cancer cell lines." (PMID 33859751, 2021). "TBX5, SPRED2, and NKX2-1 have been shown to exhibit tumor suppressor functions in lung cancer, while GMIP function has yet to be determined in cancer cells." (PMID 33227088, 2020). "Moreover, lung cancer patients with elevated expression of TCF21, NKX2-1, TBX2, and TBX5 exhibited a decreased rate of survival relative to patients with low gene expression." (PMID 37627195, 2023). "It has been previously suggested that TBX5, SPRED, and NKX2-1 may function as tumor suppressors in lung cancer, while nothing is known about the function of GMIP in any human cancer." (PMID 33227088, 2020). "Moreover, the lung cancer-specific OS rate significantly increased in patients with TBX2 subfamily high expression group than that in low expression group (TBX2 logrank P = 0.0023, TBX3 logrank P = 1.9e-5, TBX4 logrank P = 0.027, TBX5 logrank P = 2.2e−10)." (PMID 38413457, 2024). "In addition, we validated the tumor-suppressive role of IRX1, TBX5 and HSPB6 in lung cancer." (PMID 33859751, 2021). "Even though the relationshihp the development of lung cancer and TBX5 are not clear, TBX5 could significantly inhibit in vivo tumor growth, and the level of TBX5 was negatively correlated with lung cancer progression." (PMID 32810974, 2020). "Moreover, all of the eight novel hypermethylation driver genes (PCDH17, IRX1, ITGA5, HSPB6, TBX5, ADCY8, GALNT13 and TCTEX1D1) were successfully validated in an independent cohort via a pyrosequencing approach, with an AUC of 0.965 for prediction of lung cancer patients." (PMID 33859751, 2021). "The remaining eight genes are newly identified methylation drivers in lung cancer, including 5 known cancer methylation driver genes in other cancer types (HSPB6, IRX1, ITGA5, PCDH17, TBX5) and 3 novel genes that had not been previously reported (ADCY8, GALNT13 and TCTEX1D1)." (PMID 33859751, 2021).
breast carcinoma (7 papers, 2015 to 2021). "In order to more closely understand the role of TBX5 in predicting DM events, we extended our analysis to other tumor types; in particular, we focused on breast cancer, since in these patients DM is the leading cause of death." (PMID 32283719, 2020). "The increase of TBX5 drives the mesenchymal phenotype of breast cancer, promotes the EMT process, and inhibits the expression of the immune response network." (PMID 34526059, 2021). "The link between miR-10b expression and breast cancer cell proliferation is partially attributed to inhibition of the transcription factor TBX5, leading to repression of the tumor suppressor PTEN9." (PMID 28322342, 2017). "Our data suggest that, in breast cancer cells, YAP1/β-catenin complex with TBX3, which phenocopies TBX5 at BCL2L1 and BIRC5 but additionally promotes cMYC expression, potentially by combining known TEAD- and TBX3-binding elements." (PMID 26549256, 2015).